RNU6-1077P (RNA, U6 small nuclear 1077, pseudogene)
Gene: Small nuclear RNA gene on chromosome 12 (130,869,736 to 130,869,837, reverse strand). Ensembl gene ENSG00000222438.
Homologues: Orthologues: chimpanzee U6 (93% identical), macaque U6 (86% identical), rat LOC120094561 (82% identical). Paralogues in human: RNU6-1152P (82% identical), RNU6-15P (82% identical), RNU6-16P (82% identical), RNU6-298P (82% identical), RNU6-35P (82% identical), RNU6-820P (82% identical), RNU6-1 (81% identical), RNU6-1316P (81% identical), RNU6-140P (81% identical), RNU6-144P (81% identical), RNU6-14P (81% identical), RNU6-174P (81% identical), and 1284 more.